SNORD115-42 (small nucleolar RNA, C/D box 115-42)
Synonyms: HBII-52-42
Gene: Small nucleolar RNA gene on chromosome 15 (25,247,345 to 25,247,426, forward strand). Ensembl gene ENSG00000201143.
Gene Ontology:
Biological process: RNA processing
Cellular component: nucleolus
Homologues: Orthologues: chimpanzee SNORD115 (99% identical). Paralogues in human: SNORD115-12 (99% identical), SNORD115-15 (99% identical), SNORD115-4 (99% identical), SNORD115-6 (99% identical), SNORD115-9 (99% identical), SNORD115-10 (98% identical), SNORD115-11 (98% identical), SNORD115-13 (98% identical), SNORD115-14 (98% identical), SNORD115-20 (98% identical), SNORD115-29 (98% identical), SNORD115-34 (98% identical), and 37 more.